CXCR2 (C-X-C motif chemokine receptor 2)
Diseases named in the same sentence as CXCR2 in open-access papers (continued):
Sharing a sentence is not in itself a finding about the gene and the disease.
Sepsis (continued). "The transmigration of neutrophils from the vascular compartment into the infection site is driven by the interaction between chemoattractants and CXCR2 on neutrophils, which is downregulated during sepsis progression." (PMID 33912055, 2021). "It has also been shown that CXCR2 is downregulated on neutrophils during sepsis, thereby favouring infection." (PMID 33780519, 2021). "Of all neutrophil functions examined by our study, we can only affirm a reduction of CXCR2 surface level as sepsis-related." (PMID 33424860, 2020). "Molecules known to participate in the mechanism of neutrophil migration, such as GRK2 and CXCR2, were shown to be increased and decreased, respectively, in neutrophils obtained from experimentally-induced sepsis by cecal ligation and puncture (CLP)." (PMID 33111742, 2020). "As patients progress into the less dynamic phase of the disease, CXCR2 surface level increases so that, by the end of the week, the difference of CXCR2 surface level between sepsis and infected patients disappears." (PMID 33424860, 2020). "It has been well established that the decrease of CXCR2 expression impairs neutrophil migration, especially in sepsis, in which a great amount of inflammatory cytokines and chemokines is released to the blood, causing a complex systemic inflammation." (PMID 32701055, 2020). "MFI of CD64, CCR2, and CXCR2 surface receptors stratified by sepsis status† (n = 30: septic shock = 19, infection = 11)." (PMID 33424860, 2020). "In sepsis, the reduction of neutrophils migration is related to the down regulation of CXCR2 protein expression on circulating neutrophils surface." (PMID 32701055, 2020). "CXCR2 surface level is related to sepsis activity while CD64 and CCR2 surface levels link to sepsis via infection." (PMID 33424860, 2020). "As seen in sepsis, our findings showed decrease CXCR2 expression and great amount of systemic CXCL1 levels in serum of ethanol-fed mice after A. fumigatus infection." (PMID 32701055, 2020). "Previous studies have revealed that the decreased expression of CXCR2 impaired neutrophil recruitment to the infection site and played a major role in the poor outcome secondary to the sepsis." (PMID 30233596, 2018). "Strikingly, a negative correlation between CXCR2 expression and Wip1 was identified in our patients, indicating a critical role of Wip1 in regulating CXCR2 expression on human neutrophil during sepsis." (PMID 28878779, 2017). "Our results suggest that Mincle-mediated GRK2 regulation plays an important role in maintaining high expression of CXCR2 and improving neutrophil infiltration, thus reducing the mortality rate of sepsis." (PMID 28112221, 2017). "Based on these results, we then explored the possibility of Wip1 inhibitor treatment in reversing the downregulated expression of CXCR2 on human neutrophils found during sepsis in vitro." (PMID 28878779, 2017). "Pharmacological inhibition of CXCR2 with SB225002 also resulted in the abrogation of the prolonged survival in Wip1 KO mice after CLP-induced sepsis." (PMID 28878779, 2017). "CXCR2 was found to be reduced in the neutrophils of mice and patients with severe sepsis 50, 51, 52, and neutrophils in these patients also displayed decreased chemotaxis response to fMLP, leukotriene B4 or IL‐8 in vitro." (PMID 28244690, 2017). "We demonstrated that pharmacological inhibition of Wip1 with its inhibitor CCT007093 can significantly improve the outcome of sepsis with increased accumulation of neutrophils in the peritoneal cavity mediated by decreased internalization of CXCR2." (PMID 28878779, 2017). "In contrast, treatment of mice subjected to severe sepsis with an H2S donor has the opposite effect, resulting in increased CXCR2 expression on circulating neutrophils, increased neutrophil migration to the infection focus, and improvement survival." (PMID 27199981, 2016).
Sepsis (continued). "Among the mechanisms leading to the failure of neutrophil migration, it has been shown that CXCR2 is internalized in circulating neutrophils from mice or patients with severe sepsis." (PMID 27199981, 2016). "In a study of sepsis, IL-33 can reverse the decreased expression of CXCR2 in neutrophils through the inhibition of GRK2." (PMID 27721573, 2016). "Although IL-33, a member of the IL-1 family, was the first molecule described to preserve CXCR2-mediated migration of neutrophils in sepsis, we found that the fibrate-mediated stabilization of CXCR2 occurred independently of this IL-33-mediated pathway." (PMID 24755316, 2014). "IL-33 has beneficial effects in experimental sepsis, enhancing the accumulation of neutrophils through the upregulation of CXCR2 via GRK2-dependent pathways at the site of infection and reducing the inflammatory response in systemic sites." (PMID 25614712, 2014). "Accordingly, application of a synthetic CXCR2 inhibitor completely abrogated the protective effects of fibrates in septicemia in vivo." (PMID 24755316, 2014). "Down-regulation of CXCR2 in severe sepsis also results in failure of neutrophil migration that is associated with enhanced susceptibility to bacterial infection." (PMID 22745844, 2012). "Likewise, ALPL and IL8RB/CXCR2 were quite variable in the more severe sepsis group with 3 additional patients showing abnormal scores with >25% change." (PMID 41385588, 2025). "Interestingly, although CXCR2 was identified as the specific marker of N00, it was also upregulated in almost all neutrophil subpopulations except N02 in sepsis patients compared to controls." (PMID 39887584, 2025). "Consequently, subsequent functional experiments and clinical studies are urgently warranted to further validate the feasibility and safety of ITGAM and CXCR2-targeted interventions for sepsis treatment." (PMID 41259376, 2025). "In this study, we confirmed that CXCR2−/− mice fail to recruit neutrophils to the brain in a murine SE model from LPS-induced sepsis, but there is a similar level of adhesive neutrophils on the surface of cerebral endothelial cells, which is also verified by CXCR2 inhibitor SB225002." (PMID 39062109, 2024). "Furthermore, a recent original study revealed that macrophagic extracellular vesicle CXCL2 can aggravate the progression of sepsis via recruiting and activating the neutrophil CXCR2/PKC/NOX4 axis." (PMID 40115159, 2024). "Indeed, decreased neutrophil CXCR2 expression in sepsis correlates with the Apache II severity score and there is an association between high levels of circulating OLFM4+ neutrophils and mortality." (PMID 37048076, 2023). "Thus, there seems to be three different intracellular signaling events/pathways (i.e., TLR, TNFα, and PI3Kγ) that contribute to the internalization and thereby the reduction of CXCR2 cell surface expression in neutrophils in sepsis." (PMID 37048076, 2023). "However, despite some protective mechanisms, systemic CXCR2 inhibition ultimately aggravates organ damage and increases mortality in murine sepsis models." (PMID 36451225, 2022). "A lack of CXCR2 expression during infection has been linked to neutrophil dysfunction and has been used to delineate between patients with sepsis or infection." (PMID 36054235, 2022). "CXCR2 in sepsis is globally downregulated in bone marrow and neutrophils." (PMID 36451225, 2022). "Besides IL-17, CXCR2 plays a crucial role in the migration of neutrophils to infected sites during sepsis." (PMID 35003518, 2021). "In experimental mouse models of sepsis, GRK2 upregulation in neutrophils was associated with the decreased expression of CXCR2 at the cell surface and a subsequent decrease in the migration of neutrophils to infection sites, resulting in shorter survival of the mice." (PMID 33466410, 2021).
Sepsis (continued). "Sepsis is one of the well-established diseases resulting in specific patterns of neutrophil dysfunctions; increased CD64 and CCR2 surface levels; decreased CXCR2 surface level; apoptosis delay; and increased NETosis are widely-cited sepsis-related neutrophil dysfunctions." (PMID 33424860, 2020). "Additionally, during early sepsis, patients with more severe disease have a significantly lower CXCR2 surface level than those with milder disease." (PMID 33424860, 2020). "Based on our observation, abnormal neutrophil migration due to decreased CXCR2 surface receptors should be considered the immunopathological feature, which could act as a marker for distinguishing sepsis from infected patients at the onset of the disease." (PMID 33424860, 2020). "In addition, our study found that a reduction of CXCR2 surface level is related to sepsis, even in the presence of infection." (PMID 33424860, 2020). "Indeed, the treatment with IL-33 improves the sepsis outcome due to inhibition of LPS-induced CXCR2 internalization, which maintains the neutrophil migration toward the infectious foci." (PMID 29867945, 2018). "Indeed, the recruitment of neutrophils to foci of infection is markedly reduced—along with reduced expression of CXCR2 on the surface of neutrophils—in sepsis patients." (PMID 28112221, 2017). "The paralysis of neutrophils observed during sepsis has been related to low cell surface expression of CXCR2, which is caused by increased internalization but not by the reduced mRNA levels." (PMID 28878779, 2017). "Interestingly, fenofibrate reportedly preserved expression of CXCR2 on neutrophils and facilitated neutrophil migration, offering protection in sepsis." (PMID 28287432, 2017). "Since pharmacological inhibition of CXCR2 resulted in the abrogation of the prolonged survival in Wip1 KO mice, Wip1 inhibition-mediated prevention of CXCR2 internalization is the key event for the improved outcome of sepsis in Wip1 KO mice." (PMID 28878779, 2017). "However, the unaltered expression of FPR1 is critical for the perseverance of the functional response to fMLP, compared with the decreased expression of CXCR1 and CXCR2 and the impaired response to its ligand, IL-8, in murine sepsis." (PMID 27144520, 2016). "Moreover, PLD2 also induces the aggravation and drives mortality in sepsis by inhibiting the formation of neutrophil extracellular trap and reducing the expression of CXCR2." (PMID 27721573, 2016). "The next two parameters include the decay rate in filter Eq (which determines the delay between pathogen generation and resulting neutrophil entry into circulation during sepsis) followed by the parameter controlling transition rate of killer neutrophil to the dual phenotype by CXCR2." (PMID 26468651, 2015). "Although the results that Smaducin-6 restored LPS-induced CXCR2 reduction are similar with those recently obtained upon IL-33 treatment in sepsis, the mechanism may be different." (PMID 25766838, 2015). "Both FPR1 and CXCR2 have been shown to be downregulated by induction of GRK2 in sepsis." (PMID 24755316, 2014). "Application of cell-penetrating lipopeptides, which block CXCR1- and CXCR2-signaling, reversed the lethal sequelae of sepsis, including multi-organ failure and disseminated intravascular coagulation in mice, indicating that CXCR2 is very important in sepsis." (PMID 22936934, 2012). "Indeed, peripheral neutrophils during polymicrobial sepsis exhibit only weak CXCR2 expression due in part to TLR activation by microbial ligands." (PMID 23316483, 2012). "CXCR2 is also involved in pathogenesis of chronic inflammation, sepsis and atherosclerosis." (PMID 20419088, 2010). "Moreover, sepsis triggers massive neutrophil release from the bone marrow, flooding the bloodstream with immature cells and impairing chemotaxis through C-X-C chemokine receptor type 2 (CXCR2) desensitisation, which undermines targeted migration to infection sites." (PMID 41124072, 2025).
Sepsis (continued). "The CXCR2 is a member of the seven-transmembrane domain rhodopsin-like G protein-coupled receptors, known to have a role in immune response processes, chronic inflammation, and sepsis, as well as in tumorigenesis, angiogenesis, and metastases of several human cancers." (PMID 37445908, 2023). "However, since immature neutrophils also displayed low or negative expression of CXCR2, the downregulation of CXCR2 on neutrophils in patients with sepsis may also partly attribute to the presence of immature neutrophils." (PMID 33912055, 2021). "In contrast to the lack of CXCR2 function that impacts neutrophil function during sepsis, the effects of CCR2 were associated with increased function, demonstrated by the finding that severity of patient illness correlated positively with increasing neutrophil chemotaxis to CCR2 ligands." (PMID 30931316, 2019). "Therefore, high levels of cytokines could aggravate sepsis by reducing neutrophil migration via CXCR2 downregulation." (PMID 28112221, 2017). "Mechanistically, in severe sepsis, components of bacteria (such as TLR2 and TLR4 ligands) or mediators of inflammation may reach the circulation and activate circulating neutrophils leading to loss of CXCR2 from the surface of neutrophils." (PMID 26147469, 2015). "While CXCR2 is important for leukocyte extravasation into inflamed tissue and might be highly relevant for bacterial clearance and survival in bacteria-induced pulmonary inflammation, it has deleterious effects in sepsis." (PMID 22936934, 2012). "The ROC curve analysis revealed that ITGAM, CXCR2, and FCGR3B exhibited high classification accuracy (AUC >0.9) between the Sepsis and Control groups, indicating their strong potential for early diagnosis." (PMID 41259376, 2025). "In sepsis, the chemokine CXCL2 and its receptor CXCR2 play a critical role in neutrophil and monocyte recruitment and promotes their migration to inflammatory sites." (PMID 40977737, 2025). "Receiver operating characteristic (ROC) curve analysis demonstrated that ITGAM, CXCR2, and FCGR3B exhibited extremely high accuracy in distinguishing sepsis from controls (with an area under the curve greater than 0.9)." (PMID 41259376, 2025). "Cummings and colleagues investigated the effect of severe sepsis on the expression and function of the two CXC chemokine receptors on circulating polymorphonuclear neutrophils and found that CXCR2 expression was reduced by 50% in septic patients." (PMID 40977737, 2025). "Particularly, HD granulocytes showed higher levels of the PMN-expressed Cell Membrane pathway genes CXCR2 and CEACAM4 in SIRS than sepsis." (PMID 39434093, 2024). "CXCR2 is a receptor for eight CXC chemokines (CXCL1-8), which can drive innate immune cells to infiltrate remote organs in sepsis and seems to have a synergistic effect with lipid signaling." (PMID 36891309, 2023). "Higher levels of IL-8 are positively connected with the increased severity of numerous illness outcomes, and IL-8 binding to one of its receptors (IL-8RB/CXCR2) enhances blood vessel permeability (e.g., sepsis)." (PMID 36360315, 2022). "The chemokine receptor CXCR2 and its ligands, especially CXCL8, are crucial mediators for the progression of liver inflammation and liver failure in sepsis." (PMID 36451225, 2022). "Thus, restoring the expression of CXCR2 on neutrophils might be potential sepsis therapy." (PMID 36451225, 2022). "For example, the blockade of PI3K restored CXCR2 surface levels on neutrophils via inhibition of GRK2 in a septic mouse model and translated into a better prognosis of sepsis." (PMID 36451225, 2022). "To address the mechanism of neutrophil migration to muscle, we examined expression of CXCR2 and CCR2 of neutrophils in muscle after sepsis, which are known as neutrophil migration factors." (PMID 36389802, 2022). "In our current study, we mainly focused on the CXCR2 signaling pathway and investigated the role of TMZ during sepsis." (PMID 30233596, 2018).
Sepsis (continued). "Pharmacological inhibition of Wip1 with its inhibitor can also prevent the internalization of CXCR2 on human neutrophils treated with lipopolysaccharides in vitro and significantly improve the outcome in CLP-induced sepsis model." (PMID 28878779, 2017). "It has been shown that the expression of CXCR2 is reduced on the cell surface of neutrophils and migratory response to the CXC chemokines is markedly suppressed in PMNs from patients with sepsis compared with normal PMNs." (PMID 23874546, 2013). "Blocking or eliminating CXCR2 decreased liver injury and mortality in a murine model of cecal ligation and puncture (CLP)-induced sepsis." (PMID 22936934, 2012). "Consistent with the observation of the increase in CXCR2+ and CD274+IL1RN+ neutrophil subpopulations in sepsis, the amplification of CXCR2+ and PD‐L1+ subpopulations was observed in both blood and BALF neutrophils in immunosuppressive sepsis patients." (PMID 39887584, 2025). "Moreover, the amplification of CXCR2+ subpopulation and the enhanced CXCR2 MFI in neutrophils from peripheral blood and BALF in CLP‐induced sepsis mice were observed, especially in the immunosuppressive period (day 7)." (PMID 39887584, 2025). "Indeed, in addition to its well-established role as a neutrophil chemoattractant through CXCR1 and CXCR2, IL-8 (CXCL8) acts as a stage-dependent mediator in sepsis." (PMID 41268545, 2025). "Most notably, the CXCR2 binding signature motif of MIF is not present in MIF-2, in line with recent findings that MIF, but not MIF-2, recruit macrophages via CXCR2 in a polymicrobial sepsis model." (PMID 40055309, 2025). "Next, the ROC curves show that the ITGAM, CXCR2, and FCGR3B expression levels provide high accuracy for classifying the Sepsis and Control group (AUC > 0.9); MMP9, MPO, and CTSG expression levels exhibit moderate accuracy for this classification (0.7 < AUC < 0.9)." (PMID 41259376, 2025). "In our neonatal E. coli-induced sepsis mouse model, we found significantly upregulated CXCR2 expression levels in splenic mononuclear cells but not neutrophils of IL-27 receptor KO pups." (PMID 40977737, 2025). "In addition, CXCR2 signalling-induced and reactive oxygen species (ROS)-dependent NET formation has been demonstrated to be a therapeutic target in sepsis." (PMID 37533081, 2023). "Non-survivors of sepsis showed higher CXCR2 expression on neutrophils and more neutrophil migration dysfunction than survivors." (PMID 36891309, 2023). "But only CXCR2 rather than CXCR1 is reduced on neutrophils in patients with sepsis, and the interleukin-8 mediated chemotaxis is impaired." (PMID 36891309, 2023). "Considering AKI (acute kidney injury) as a decompensating besides sepsis, we found a decrease in the percentage of neutrophils, CD11b+CD66b+, CXCR1+, and CXCR2+ on CD11b+CD66b+ cells in AKI patients compared to no AKI in decompensated cirrhosis with sepsis." (PMID 35681439, 2022). "Thus, the DE genes identified in this study, such as OLFM4, MME, CXCR2,CEACAM8, and ELANE, probably take part in pediatric sepsis development by regulationof neutrophil function." (PMID 33503200, 2021). "CXCR1 and CXCR2 in human neutrophils are well established receptors for the neutrophil chemoattractant, IL-8, and others have shown modulated CXCL1 and chemokine receptor expression by IL-33 in bacterial infections and sepsis in animal models." (PMID 34266437, 2021). "A previous study showed that blocking CXCR2, the main receptor of CXCL1 and CXCL2, effectively decreased alveolar accumulation of neutrophils in the CLP model of sepsis, demonstrating that CXC chemokines are important regulators of pulmonary infiltration of neutrophils in septic lung injury." (PMID 34884728, 2021). "During non-severe sepsis, neutrophils expressing C-X-C Motif Chemokine Receptor 2 (CXCR2) are recruited from the blood to the site of infection in response to C-X-C Motif Chemokine Ligand 2 (CXCL2) and other chemoattractant." (PMID 34200950, 2021).